TREM2 (triggering receptor expressed on myeloid cells 2)
Diseases named in the same sentence as TREM2 in open-access papers (continued):
Sharing a sentence is not in itself a finding about the gene and the disease.
hepatocellular carcinoma (38 papers, 2019 to 2025). A malignant tumor that arises from hepatocytes. "Despite minimal data for colon cancer, TREM2 was recently associated with a tumour suppressor role in hepatocellular carcinoma by decreasing metastasis through interaction with epithelial to mesenchymal transition (EMT)." (PMID 30857282, 2019). "Interestingly, our analysis of RASF-MØ revealed an upregulation of TREM2, whose expression has been associated with a subset of macrophages with a proangiogenic and immunosuppressive profile in Hepatocellular Carcinoma patients." (PMID 36930354, 2023). "Scientists have identified a population of cells within hepatocellular carcinoma (HCC) tumor tissues that exhibit characteristics similar to lipid-associated macrophages (LAMs), that have been termed TREM2+ LAM-like cells." (PMID 40242752, 2025). "TREM2+ TAMs are highly enriched in hepatocellular carcinoma and are an indicator of shorter survival in these patients." (PMID 39113887, 2024). "For example, TREM2+ macrophages have been shown to suppress CD8+ T-cell infiltration in hepatocellular carcinoma, and SPP1+ macrophages interact with FAP+ fibroblasts to remodel the extracellular matrix." (PMID 39702278, 2024). "The expression level of TREM2 was significantly decreased when Ech was treated with HepG2 cells or DEN-induced hepatocellular carcinoma mouse model, and the inhibitory effect of Ech was reduced by overexpression of TREM2." (PMID 35571569, 2022). "Three maker genes were found in liver carcinoma of HPA database (TREM2 and GPR34 from macrophage, PDCD1 from Treg cell), which indicated that macrophages and Treg cells existed in liver carcinoma." (PMID 36221095, 2022). "In contrast, the upregulation of TREM2 expression is considered to hamper tumor progression in hepatocellular carcinoma, colorectal cancer, and lung cancer." (PMID 36230558, 2022). "In contrast, a recent study showed that TREM2 expression was decreased in hepatoma cells and acted as a tumor suppressor." (PMID 35359989, 2022). "Recently, several groups reported TREM2 as a novel tumor suppressor in colorectal and hepatocellular carcinoma." (PMID 33980160, 2021). "COL6A3 and KLK7 in CRCs, SHC3 in hepatocellular carcinomas, and TREM2 in gastric cancers and renal cell carcinomas are associated with tumor growth." (PMID 33037736, 2020). "These cells express the marker genes CD9 and TREM2, a tumor suppressor in hepatocellular carcinoma, as well as the markers CAPG and GPNMB." (PMID 33332768, 2020). "Prior studies have implicated these TRIP13 targets in the progression of various cancers, including COL6A3 and KLK7 in CRCs, SHC3 in hepatocellular carcinomas, and TREM2 in gastric cancers and renal cell carcinomas." (PMID 33037736, 2020). "Overexpression of TREM2 in hepatoma cells remarkably prevented tumor metastasis in vitro and in vivo." (PMID 30683932, 2019). "Moreover, the TREM2+ TAMs enrichment was a main trait in hepatocellular carcinoma patients who were resistance to atezolizumab + bevacizumab therapy." (PMID 41253786, 2025). "TREM2+ LAMs were also detected in hepatocellular carcinoma and exhibited an immunosuppressive function by recruiting suppressive Treg cells via the CCL20/CXCL9/CXCL10/CXCL12–CXCR3 axes, which may compromise the antitumour response." (PMID 38303024, 2024). "Specifically, TREM2 in TAMs promotes tumor progression in colorectal carcinoma, ovarian carcinoma and hepatocellular carcinoma (HCC) following transarterial chemoembolisation (TACE) by remodeling the landscape of tumor-infiltrating myeloid cells and weakening the anti-tumor ability of CD8+ T cells." (PMID 39135069, 2024). "Furthermore, TREM2 has shown potential as a therapeutic target in cancer, particularly in hepatocellular carcinoma." (PMID 39113887, 2024). "Similarly, in the context of other liver pathologies, such as acute liver injury, primary sclerosing cholangitis and hepatocellular carcinoma, TREM2 has been shown to exert a protective function." (PMID 36766683, 2023).
hepatocellular carcinoma (continued). "Interestingly, experimental models of hepatic carcinoma in the context of liver fibrosis yielded the opposing effect, with TREM2 promoting fibrosis but inhibiting tumorigenesis." (PMID 36741909, 2023). "However, the role of TREM2 signaling in the tumor microenvironment of hepatocellular carcinoma (HCC) remains poorly understood." (PMID 35359989, 2022). "Furthermore, TREM2 can acts as a tumor suppressor in colorectal carcinoma and hepatocellular carcinoma through WNT1/β-catenin and extracellular signal-regulated kinase signaling or PI3K/AKT/β-catenin signaling." (PMID 33980160, 2021). "The suppression of TREM2 expression contributed to a substantial increase in cell motility, migration, and invasion ability of hepatoma cells, while TREM2 stable overexpression produced the opposite effect, as detected by scratch, transwell migration and invasion assays." (PMID 30683932, 2019). "In nonalcoholic steatohepatitis (NASH, also known as metabolic dysfunction-related steatohepatitis, MASH), macrophages expressing Trem2 play a key role in promoting its development into hepatocellular carcinoma (HCC)." (PMID 41000074, 2025). "For example, after operating TACE of hepatocellular carcinoma, TREM2+ macrophages inhibit CD8+ T cells infiltration which causes the recurrence and progression of HCC." (PMID 38914803, 2024). "Although overexpression of TREM2 is correlated with poorer prognosis in multiple tumors, including gastric, hepatic, and ovarian carcinoma, TREM2 has been shown to suppress tumorigenesis of hepatic carcinoma, in experimental models of hepatic carcinoma in the context of liver fibrosis." (PMID 36741909, 2023). "Meanwhile, Mφ_APOE cluster, preferentially enriched in tumor tissue, was similar to tumor-associated macrophages (TAMs) in hepatocellular carcinoma (HCC) and the lipid-associated macrophages in adipose tissue by expressing APOE, TREM2, C1QA, and GPNMB30,31." (PMID 35999201, 2022). "In hepatocellular carcinoma (HCC) patients, the contribution of TREM2 macrophages seems to be more controversial." (PMID 35746551, 2022). "However, TREM2’s function in malignant diseases, especially in hepatocellular carcinoma (HCC) remains unknown." (PMID 30683932, 2019). "In hepatocellular carcinoma (HCC), TREM2 is highly expressed on myeloid cells in the tumor microenvironment and drives an immunosuppressive program." (PMID 40821795, 2025). "Moreover, C1Q+ macrophages in sAH express GPNMB, TREM2, SPP1, and CD9, resembling LAMs, which are reported in liver cirrhosis and hepatocellular carcinoma (HCC)." (PMID 40962953, 2025). "Similarly, compared to non-tumoral tissue, Trem-2 expression was increased in tumors from both mice and patients with hepatocellular carcinoma (HCC)." (PMID 33802948, 2021).
ischemic stroke (34 papers, 2013 to 2025). A stroke disorder caused by obstruction of blood flow to the brain, due to thrombotic (local blood clot formation) or embolic (due to a blood clot or other material traveling from another site) event. "This study provides insights into the potential pathway of TREM-1 and TREM-2 as a future biomarker for stratifying high-risk patients with ischemic stroke." (PMID 39062850, 2024). "We next sought to further elucidate the mechanisms that Trem2 regulates microglia‐associated immunometabolism in ischemic stroke models." (PMID 38151703, 2024). "Deficiency in TREM2 exacerbates outcomes after ischemic stroke by diminishing efferocytosis of dying neurons and microglia, underscoring its pivotal role over circulating macrophages in ischemic conditions." (PMID 39660125, 2024). "This possibility has also been supported by other work showing impaired angiogenesis in TREM2-deficient mice in the ischemic stroke model." (PMID 36389767, 2022). "TREM2 deficiency can lead to worsened outcomes after ischemic stroke by decreasing the phagocytosis of injured neurons." (PMID 35082781, 2021). "This study, in addition, strongly suggested that Trem2‐Igf1 signaling axis orchestrated this microglial phenotype shift during ischemic stroke, and immunometabolism underlying microglial transformation could be pharmacologically or genetically modulated." (PMID 38151703, 2024). "Deficiency in Trem2 may dampen microglial aerobic respiration processes and physiological functions, which subsequently exacerbates ischemic stroke‐induced brain injuries." (PMID 38151703, 2024). "The repair of white matter injury is of significant importance for functional recovery after ischemic stroke, and the up-regulation of triggering receptors expressed on myeloid cells 2 (TREM2) after ischemic stroke is neuroprotective and implicated in remyelination." (PMID 36829205, 2023). "TREM2 deficiency dampens microglial phagocytosis of neurons, which further exacerbates ischemic brain injuries, indicated the neuroprotective role of Trem2 in ischemic stroke." (PMID 35794095, 2022). "Interestingly, a gene-based study identified four genes, which included TREM2, shared by AD and ischemic stroke, implying TREM2-relevant immune signaling is one of the common pathogenesis underlying AD and ischemic stroke." (PMID 35414082, 2022). "Interestingly, a very recent study demonstrated circulating soluble TREM2 to be associated with death and cardiovascular events in patients with ischemic stroke, a population with a high pretest probability of concomitant coronary atherosclerosis." (PMID 36361908, 2022). "Particularly in acute ischemic stroke (AIS), researches have shown that the TREM2-IGF1 axis and the TREM2-TGF-β1/Smad2/3 axis exert neuroprotective effects after ischemic stroke by regulating the functions and metabolic characteristics of microglia." (PMID 40242752, 2025). "In an ischemic stroke model, Nhe1 cKO microglia showed similar upregulation of the TREM2 gene, along with activation of the LXR/RXR pathway and enhanced phagocytic activity." (PMID 40864831, 2025). "TREM2-KO mice exhibit a reduced subacute inflammatory response to ischemic stroke, whereas the infarct size remains unchanged." (PMID 39649720, 2024). "In the present study, we first identified a microglial subcluster up‐regulated after ischemic stroke, characterized by enhanced OXPHOS and a molecular signature of upregulated Trem2, Igf1, as well as other phagocytosis‐associated molecules." (PMID 38151703, 2024). "A previous study reported that the TREM2‐mediated microglial response to oligodendrocyte differentiation and remyelination could be promoted by physical exercise in rats after ischemia stroke and that ischemic stroke was also associated with abundant WMI pathology." (PMID 38649789, 2024).
ischemic stroke (continued). "Mechanistically, Igf1 serves as one of the major down‐stream molecules of Trem2, and Trem2‐Igf1 signaling axis regulates microglial functional and metabolic profiles, exerting neuroprotective effects on ischemic stroke." (PMID 38151703, 2024). "Taken together, Trem2 functions as a pivotal regulator of microglial activities and aerobic respiration in ischemic stroke, which affects microglial morphology, phenotypes and functions." (PMID 38151703, 2024). "To further illustrate the downstream signals of Trem2 in microglia after ischemic stroke, we conducted a trend analysis in the bulk RNA‐Seq data." (PMID 38151703, 2024). "Trem2‐Igf1 signaling axis plays pivotal roles in microglial activities against ischemic stroke injuries." (PMID 38151703, 2024). "The strategy of microglial depletion and repopulation likely acts through depletion and repopulation of IGF1 and TREM2 positive microglial subpopulation, which serves as a potential therapeutic approach in ischemic stroke." (PMID 38151703, 2024). "Conclusively, the transcriptional profiles of microglia suggested increased frequency of a subcluster during ischemic stroke, with molecular signature of upregulated Trem2 and Igf1, and functional features of neuroprotective and pro‐repairing properties." (PMID 38151703, 2024). "In this study, we aimed to investigate the effect of TREM2 on POCD in a mouse model of ischemic stroke, with a focus on the mechanisms involving TREM2 and the PI3K/Akt signaling pathway." (PMID 39758888, 2024). "Upon ischemic stroke, microglia up‐regulate Trem2 expression levels, which subsequently boosts Igf1 expression and affects microglial metabolic profiles as well as cellular functions." (PMID 38151703, 2024). "Through the aspect of post-ischemic inflammatory response and neuronal apoptosis, TREM2 protects against cerebral ischemia/reperfusion injury in ischemic stroke." (PMID 37435171, 2023). "A high-salt diet can weaken macrophage efferocytosis dependent on Trem2 after ischemic stroke, thereby aggravating neuroinflammation." (PMID 37047321, 2023). "Triggering receptor expressed on myeloid cells 2 (TREM2) confers strong neuroprotective effect by suppressing neuroinflammatory response in experimental ischemic stroke." (PMID 36353688, 2022). "Docosahexaenoic acid (DHA) treatment enhances mesencephalic astrocyte-derived neurotrophic factor (MANF), reduces the expression of TREM2 and ischemic brain damage, activates neurogenesis, and promotes functional recovery after experimental ischemic stroke." (PMID 36212660, 2022). "Accumulating evidence indicated that TREM2 alleviated neuroinflammation in experimental ischemic stroke." (PMID 36353688, 2022). "HSD inhibited the efferocytic capacity of macrophages by downregulating TREM2 expression, thus impeding inflammation resolution after ischemic stroke." (PMID 33845849, 2021). "After ischemic stroke, cell debris of injury induce microglial phagocytosis via the TREM-2/DAP12/ERK/PKC pathway." (PMID 34276309, 2021). "The data encourage further research on the therapeutic potential of enhancing TREM2 signaling in patients with ischemic stroke, especially those with high-salt intake." (PMID 33845849, 2021). "The results indicated that TREM2 expression in monocytes/macrophages favored efferocytosis and the subsequent inflammation resolution after ischemic stroke." (PMID 33845849, 2021). "In recent years, accumulating evidence has shown that TREM2 confers strong neuroprotective effects by attenuating neuroinflammation in experimental ischemic stroke." (PMID 32466767, 2020). "While the activation of postischemic inflammation by the innate immune response is an essential step in the progression of cerebral ischemic injury, the significance of TREM2 in the pathogenesis of ischemic stroke remains to be further elucidated." (PMID 32757264, 2020).
ischemic stroke (continued). "Triggering receptor expressed on myeloid cells 2 (TREM2) confers strong neuroprotective effects by attenuating neuroinflammation in experimental ischemic stroke." (PMID 32466767, 2020). "Despite the great promise for TREM2 in ischemic stroke, TREM2 signaling has opposite effects in peripheral nerve injury including motor nerve injury and neuropathic pain, and after traumatic brain injury." (PMID 31379859, 2019). "Nonetheless, the role of TREM2 in ischemic stroke is mainly considered beneficial, and the same holds for its role in AD and demyelinating disease although few studies report a detrimental effect of TREM2 signaling in these neural diseases." (PMID 31379859, 2019). "This short review aims to elaborate on these TREM2-mediated microglial functions in the pathobiology and resolving of ischemic stroke." (PMID 31379859, 2019). "Based on these TREM2 effects on microglial function and the role of microglia in ischemic stroke, several mechanisms are proposed to be mediated by microglial TREM2 activity." (PMID 31379859, 2019). "Agonists of TREM2 would be expected to repair cerebral ischemia/reperfusion injury, making TREM2 an attractive new clinical target for the treatment of ischemic stroke and other cerebrovascular diseases." (PMID 28592261, 2017). "Manipulating TREM2 expression levels in vitro and in vivo significantly regulated the production of pro- and anti-inflammatory mediators after ischemic stroke." (PMID 28592261, 2017). "To investigate the role of TREM2 during ischemic stroke, we first examined cultured primary microglia cells that had been subjected to OGDR." (PMID 28592261, 2017). "After ischemic stroke, TREM2-KO mice exhibit reduced microglial activity, with decreased transcription of pro-inflammatory cytokines TNFα, IL-1α, and IL-1β, as well as reduced transcription of chemokines CCL2 (MCP1), CCL3 (MIP1α), and chemokine receptor CX3CR1." (PMID 39649720, 2024). "We first identified that upregulation of Igf1 was highly dependent on Trem2 both in vivo and in vitro, suggesting that Igf1 may serve as a potential downstream signal of Trem2 in ischemic stroke." (PMID 38151703, 2024). "Thus, understanding how to activate Trem2‐Igf1 signaling axis in microglia plays crucial roles, is key to harness neuroprotective potential for the treatment of ischemic stroke." (PMID 38151703, 2024). "In addition, TREM2 has been shown to play protective roles against other CNS injuries, such as intracerebral haemorrhage, subarachnoid hemorrhage, ischemic stroke, and TBI." (PMID 38649789, 2024). "Additionally, the knockdown of endogenous TREM2 by TREM2 shRNA exacerbated neurological deficits and reduced TREM2 expression in ischemic stroke mice." (PMID 39758888, 2024). "The results of the western blot showed that ischemic stroke downregulated the expression of TREM2 at the protein level in the hippocampus while EE reversed its effect (p < 0.05 for Sham+SE vs. PT + SE; p < 0.05 for Sham+SE vs. Sham+EE; p < 0.01 for PT + SE vs. PT + EE)." (PMID 39758888, 2024). "Furthermore, a high-salt diet has been shown to reduce the efferocytic capacity of macrophages by downregulating TREM2 expression, thereby hindering the resolution of neuroinflammation post-ischemic stroke." (PMID 39660125, 2024). "Likewise, previous evidence revealed that TREM2 exerted robustly neuroprotective roles by anti-inflammation in several types of pathophysiological events, such as ischemic stroke, intracerebral hemorrhage and neurodegenerative diseases." (PMID 37658943, 2023). "In addition, TREM2 also showed an antineuroinflammatory effect in experimental ischaemic stroke and subarachnoid haemorrhage." (PMID 36463233, 2022). "Moreover, we suggest that MANF and TREM2 are an attractive target as a therapeutic avenue for ischemic stroke and other cerebrovascular diseases." (PMID 32757264, 2020).